CTLA4 (cytotoxic T-lymphocyte associated protein 4)
Diseases named in the same sentence as CTLA4 in open-access papers (continued):
Sharing a sentence is not in itself a finding about the gene and the disease.
tumor (continued). "However, TILs subjected to CTLA-4 blockade during tumor fragment cultures expanded to greater levels compared to TILs from tumor fragment cultures in IL-2 only (median 1,600 and 1,800-fold vs. 1,300 and 1,400-fold)." (PMID 32127601, 2020). "On the other hand, patients with EGFR-TKI sensitive NSCLC might rather benefit from combinatorial treatment with anti-CTLA-4 antibody, since anti-PD-L1 antibodies can only be efficient in tumor cells with high PD-L1 expression." (PMID 32486375, 2020). "In addition, combination group showed significantly smaller tumor volume than CTLA4 mAb group at 19 days after NIR-PIT (p < 0.05, Mann–Whitney U test)." (PMID 32937841, 2020). "This site-specific delivery increased tumor infiltrating lymphocytes, resulted in superior tumor growth inhibition, arrested metastatic spread, and induced complete anti-tumor responses when compared with systemic anti-CTLA-4 antibody administration." (PMID 32942725, 2020). "Interestingly, they activated NK cells, exhibited cytotoxicity against cancer cells by inducing ADCC and inhibited tumor cell growth by affecting CTLA-4 downstream pathways in a similar fashion to CD-80 and CD-86 ligands and differently from Ipilimumab." (PMID 32781690, 2020). "Furthermore, in a murine model with AML, B7-1, the specific ligand of CTLA-4, is increased in tumor cells, which mediated the resistance to immune response and poor survival." (PMID 33150182, 2020). "Conversely, administration of PPARγ agonist rosiglitazone, an approved drug for the treatment of type II diabetes, augmented CD8+ T cytotoxicity in a myeloid cell-dependent manner and increased tumor destruction in combination with CTLA4 antibody blockade and GVAX." (PMID 32823961, 2020). "Indeed, impairment of the IFN-γ pathway through knockdown of Ifgr1 after anti-CTLA4 treatment shows enhanced tumor growth and reduced survival in mice." (PMID 31968651, 2020). "For example, in a preclinical human cancer xenograft tumor model, an oncolytic adenovirus expressing anti-CTLA-4 antibodies resulted in extremely high antibody concentrations at tumors, while plasma levels remain below concentrations reported tolerated in humans." (PMID 33172438, 2020). "Infiltration of regulatory T (Treg) cells can be seen in higher grades of malignancy regardless of tumor size and subtype, while elevated expression of CTLA-4 is associated with advanced breast tumor." (PMID 33298099, 2020). "Therefore, agents that block CTLA-4, PD-1, and PD-L1 are able to produce an anti-tumor response through immune activation." (PMID 32972006, 2020). "However, the phenotype of the TME trended to immunosuppression, and the infiltrating CD8+ T cells biased to exhaustion in the CTLA4 high group, synergizing with Tregs, ultimately leading to tumor metastasis and progression." (PMID 33117084, 2020). "Anti-PD-1, PD-L1, and CTLA-4 antibodies have shown the potential for tumor regression." (PMID 33511267, 2020). "T cell responses specific for B. Thetaiotaomicron or B. fragilis were associated with the efficacy of the CTLA-4 blockade, and the introduction of B. fragilis into germ-free mice sensitized to murine neoplasms to CTLA-4 treatment, which was ineffective in germ-free animals." (PMID 32375310, 2020). "In addition, the authors found combination therapy of localized NDV and systemic CTLA-4 or PD-1 blockade to produce antigen-dependent tumor rejection in a tumor rechallenge model." (PMID 33207653, 2020). "In addition, the function and phenotype of tumor residing Tregs are modified compared to circulating Tregs In other words, the expression of some inhibitory receptors such as CTLA-4, TIM-3, PD-1, and CD39 increases on the surface of intratumoral Tregs." (PMID 33519807, 2020).
tumor (continued). "Although the role of tumor immunity has been known for decades, the introduction of immune checkpoint inhibitors (e.g., anti-CTLA4, or PD1/PDL1 axis antagonists) as new anticancer agents quickly led to spectacular improvements in clinical outcomes, including 5 year-survival rates above 30%." (PMID 32796670, 2020). "Based on a new mechanism of action, we performed an in-depth survey of the TCGA database for genomic and RNA expression features that promote anti-CTLA-4 response, including target (CTLA-4) expression, gene signature, immune cell composition, tumor mutation burden, and ADCC/ADCP features." (PMID 31991588, 2020). "Hot tumors are characterized by a high degree of T cell and CTL infiltration both in CT and in IM of tumor; they present the higher Immunoscore, with a consistent activation of immune checkpoints PD-1, CTLA-4, TIM3, and LAG3 and a consequent impairment of T cells functions." (PMID 33986723, 2020). "Tumor cells have the ability to escape from host immunity and the role of immune checkpoint inhibitors is to target transmembrane proteins such as the CTLA4, PD1, and PD-L1 ligand." (PMID 32796670, 2020). "However, many tumor types would require alternative combinations of OVs that target other immune checkpoints beyond PD-1/PD-L1 or CTLA-4." (PMID 32411132, 2020). "Additionally, it has been revealed that treatment using an anti-KIT monoclonal antibody in a mouse colon cancer model enhanced the anti-tumor activity of anti-CTLA-4 and anti-PD-1 therapy by selectively reducing the MDSCs population." (PMID 33384962, 2020). "ACT in combination with blockade of both PD-1 and CTLA-4 has shown particularly good effects, most likely because the anti-PD-1 treatment counteracts PD-L1-mediated inactivation of T cells whereas anti-CTLA-4 enhances priming of endogenous tumor-reactive T cells." (PMID 33101304, 2020). "This study showed that treatments with anti-CTLA-4 antibody alone and tumour lysate-pulsed DCs alone led to increased intra-tumour infiltration of CD8+ T cells, decreased frequency of Treg cells, increased IFN-γ serum levels, reduced burden of pulmonary metastases and prolonged survival." (PMID 33207697, 2020). "PD-1 or PD-L1 blockade acts more directly on T cells that are already activated and resides within the TME, which may be more beneficial than single-agent CTLA-4 blockade, which generally enhances T cell priming in tumour draining lymph nodes." (PMID 33207697, 2020). "Cytotoxic T-lymphocyte-associated protein 4 (CTLA-4) acts as a brake on the surface of T cells, leading researchers to explore whether blocking CTLA-4 might augment anti-tumor T cell-mediated immunity." (PMID 33322601, 2020). "We do not observe a rise in anti-tumor antibody detectable in the serum against B78 tumors after tumor re-challenge in mice cured of B78 by RT + IT-IC + anti-CTLA-4 after B cell depletion, confirming a lack of antibody-based humoral memory response in B cell deficient mice." (PMID 32849544, 2020). "CTLA-4 and/or PD-L1 blockade in tumors has been demonstrated to act via the depletion of regulatory and immunosuppressive cell types such as Tregs and MDSCs and reinvigorating exhausted T-cells to facilitate tumor entry for more effective tumor eradication." (PMID 32793206, 2020). "Additionally, we characterized the interactions between tumor-expressed CTLA-4 and immune infiltration." (PMID 32850353, 2020). "However, high glycolysis group was associated with lower infiltration of tumor-killing immune cells such as NKT cells and higher immune checkpoints expression such as PD-L1, CTLA4, FOXP3 and IDO1." (PMID 32070368, 2020). "Our data suggest that Ipilimumab may stimulate CTLA-4-expressing tumor cells to secrete IL-2, contributing to the establishment of a favorable immunologic microenvironment, that may support the action of Ipilimumab." (PMID 32850353, 2020). "Altogether these data provided evidence that butyrate could diminish anti-CTLA-4 anti-tumor efficacy in mice." (PMID 32358520, 2020).
tumor (continued). "For example, while oncolytic virotherapy induced the infiltration of activated lymphocytes in tumors, the antitumor effect was unable to lead complete tumor regression because of treatment-induced adaptive immune resistance manifested by upregulation of CTLA-4 or PD144–46." (PMID 32111828, 2020). "Although murine studies have pointed out the efficacy of immune checkpoint inhibition using anti-PD-1, anti-Tim-3, anti-CTLA4, combinations thereof and radio-chemotherapy, it is incompletely understood which T cell population will be activated and how tumor-specific activation will be constituted." (PMID 32117316, 2020). "The blockade of CTLA-4 with anti-CTLA-4 antibodies can enhance the immune response to tumours." (PMID 32183814, 2020). "Together, these results revealed a unique transcriptomic landscape of CTLA-4-activated-like tumors that might impact relevant cancer programs locally, in the tumor cell, and in the tumor microenvironment." (PMID 32850353, 2020). "The histological analysis of MOC1 tumor one week after treatment showed that infiltration of CD8+ and CD4+ T-cells into the tumor bed dramatically increased after CTLA4 immune-checkpoint blockade alone and combined regimen of CD44-targeted NIR-PIT with CTLA4 immune-checkpoint blockade." (PMID 32937841, 2020). "Indeed, upregulation of a number of immune checkpoints, including CTLA-4 and PD-1, was observed on tumor-infiltrating T cells in both virus-injected and distant tumors." (PMID 33260685, 2020). "In addition, our results suggest that CTLA-4+ cells suppress the function of FoxP3+ T-cells and promote anti‐tumor immunity in OSCC." (PMID 32785290, 2020). "Previous studies have revealed that tumor‐intrinsic active β‐catenin signaling may lead to T‐cell exclusion, thus resistance toward anti‐PD‐L1 and anti‐CTLA4, which is consistent with the insensitivity toward immune blockade in C1 patients of our study." (PMID 31955511, 2020). "Interestingly, paired tumor biopsies from the patient donor showed a similar reduction in the CD4/CD8 ratio after dual PD-1/CTLA4 blockade." (PMID 32331230, 2020). "However, in rats receiving PD-L1–CTLA4 DNA vaccination, CCA tumor growth was inhibited, and the antibodies of PD-L1 and CTLA4 were produced." (PMID 33255375, 2020). "Similarly, CTLA-4 plays a critical role in attenuating the early activation of naïve and memory T cells and NPC patients with higher tumor CTLA-4 expression had poorer prognosis." (PMID 32331230, 2020). "Tumor and immunosuppressive cells, such as MDSCs, also inhibit antitumor responses through the interaction of immune checkpoint molecules, such as PD-1/PD-L1, CTLA-4/B7, and Gal-9/TIM-3." (PMID 32942545, 2020). "Adoptively transferred T cells may upregulate PD-1 and CTLA-4 upon chronic exposure to tumour antigens, therefore combination of ACT with ICB might be a promising strategy that will improve clinical response rates." (PMID 32183246, 2020). "In the MCA101OVA tumor model, blocking CTLA-4 could increase antigen-specific T cell responses in the tDLN; addition of butyrate could limit these responses." (PMID 32358520, 2020). "CD44-targeted NIR-PIT combined with CTLA4 blockade showed more effective tumor killing and complete remission in MOC1 tumors than NIR-PIT combined with PD-1 blockade in a previous study whereas in MC38-luc and LL/2 tumors NIR-PIT combined with PD-1 blockade was more effective." (PMID 32937841, 2020). "Furthermore, inhibition of CSN5 by curcumin sensitizes inflammation-induced tumors to anti-CTLA4 therapy in various murine tumor models." (PMID 32486375, 2020). "We confirm with the model that the anti-CTLA4 treatments allow clonal expansion in the lymph nodes, but this is not enough for an efficient immune response, because differentiation into specific T effectors is blocked by immune checkpoints in the tumour bed." (PMID 33276543, 2020).
tumor (continued). "Furthermore, we demonstrated that IL36 and CTLA-4 mAbs additively promoted antitumor immune responses and greatly prolonged survival of tumor-bearing mice." (PMID 32351508, 2020). "Besides PD-1 and CTLA-4, other co-inhibitory receptors that influence anti-tumor immune responses have been discovered." (PMID 33101304, 2020). "Activated Tregs can express PD1, PDL1 and CTLA4 to inhibit tumor-specific T lymphocytes functions." (PMID 33323544, 2020). "These CD4 effector T cells elicited by anti-CTLA-4 mAb improved anti-tumor responses by enhancing CD8 T cell infiltration, and cytolytic CD8 activity, demonstrating that PD-1 and CTLA-4 attenuate T cell activation though distinct molecular and cellular mechanisms." (PMID 32655545, 2020). "This study shows that CD3 PET imaging can help predict tumor responses to CTLA4 blockade." (PMID 33298096, 2020). "Rationalizing that tumor expression of CTLA-4 not only regulates cellular functions, but may also modulate the immune microenvironment, we inspected the immunogenicity characteristics of cell lines and tumors." (PMID 32850353, 2020). "Higher tumor infiltration likely accounts for CTLA-4/PD synergy." (PMID 33585182, 2020). "Nevertheless, the expression of ICM leads to immune escape of tumor cells and some of these ICMs (particularly the cytotoxic T lymphocyte antigen (Ag)-4 (CTLA-4), programmed cell death-1 (PD-1) and its ligand (PD-L1)) are now being blocked by monoclonal antibodies (mAbs)." (PMID 37425217, 2020). "Administration of CTLA4 mAb blocks the immunosuppressive mechanism of gMDSCs as well as Treg cells within the tumor microenvironment in MOC1 tumors, which may further confer therapeutic benefits." (PMID 32937841, 2020). "In this study, we have shown that the addition of anti-CTLA-4 antibody to tumor fragments from metastatic ovarian cancer does not only promote the outgrowth of TILs but also favors the propagation of CD8+ T cells and thus enhances the anti-tumor reactivity of TILs." (PMID 32127601, 2020). "Interestingly, within the group of patients with microsatellite stable (MSS) tumours, some also presented with increased immune infiltration, including comparably high portions of PD-1+ T cells, but also CTLA-4+ T cells." (PMID 33228141, 2020). "Tumor cells with high CTLA-4 mRNA are more sensitive to CTX but less sensitive to Everolimus." (PMID 32602545, 2020). "Specific antibodies that block CTLA-4+ cells have been used to enhance anti-tumor immune responses." (PMID 32785290, 2020). "Moreover, CD8+ tumor-infiltrating lymphocytes expressing PDCD1 (encoding PD-1) and Cytotoxic T-Lymphocyte Antigen 4 (CTLA-4) correlate with response to checkpoint blockade therapy and survival in melanoma patients." (PMID 32054102, 2020). "Thus, the increased concentration of CTLA-4 in the tumor microenvironment results in decreased activation of T cells and therefore decreased targeting and destruction of tumor cells by the body’s immune system." (PMID 32944086, 2020). "In addition, T cells express programmed death 1 (PD-1) that binds to PD-L1 or PD-L2 of other cells (e.g. tumor cells) to terminate the T cell response similarly to CTLA-4." (PMID 32944086, 2020). "Recently the study of the immune system within the TME allowed to develop new treatments based on the targeting of inhibitory receptors present on tumor infiltrating leukocytes (CTLA-4, PD-1), and later on their ligands which are expressed by other immune cells as well as tumor cells (PD-L1)." (PMID 33362787, 2020). "In addition, in a mouse model with the human FcR system, it was demonstrated that binding to FCGRIIIA is critical for optimal ADCC of Treg and tumor rejection by anti-CTLA-4 antibodies." (PMID 31991588, 2020).
tumor (continued). "Using flow cytometry, we tested for the presence of anti-tumor antibody in these serum specimens and observed the fold change in MFI of anti-tumor antibodies was significantly higher in RT + IT-IC + anti-CTLA-4 treated mice compared those cured by surgical resection (n = 7–8; p = 0.0401)." (PMID 32849544, 2020). "Multiple T cell checkpoint molecules have been described, and the blockade of either of of these two inhibitory proteins, cytotoxic T-lymphocyte antigen 4 (CTLA4) and programmed cell death protein 1 (PD-1), has resulted in clinical benefit in several tumor types." (PMID 32138216, 2020). "Clinically effective anti-CTLA-4 mAb causes tumour rejection by mechanisms that are independent of checkpoint blockade but dependent on the host Fc receptor." (PMID 32680511, 2020). "Therefore, a new generation of anti-CTLA-4 antibodies must show higher anti-tumor activity in order to achieve better outcomes." (PMID 31991588, 2020). "However, PD1 and CTLA4 genes were less expressed in the higher tumor budding grades in both patients and xenografts." (PMID 32719800, 2020). "However, KO mice derived Treg cells exhibited remarkably reduced expression of Foxp3 and CTLA4 in both tumor tissue and dLNs, suggesting a compromised stability and function of Bcl6-dificient Treg cells." (PMID 32477338, 2020). "Both CTLA-4 and PD-1 were originally identified as co-inhibitory receptors on T cells; therefore, checkpoint blockade immunotherapy has concentrated on recovering T cell-mediated anti-tumor capacity to regress tumors." (PMID 32714324, 2020). "The authors then performed a dual blockade of LAG-3 and CTLA-4 in PD-1 knockout mice, which resulted in an increase in tumor free survival to 40% of mice, as well as an increase of peritoneal CD8+ T cells and cytokine producing effector T cells, and a decrease in Tregs and MDCS." (PMID 32756436, 2020). "Anti-CTLA4 therapy could strongly enhance the amplitude of vaccine-induced antitumor responses in many poorly immunogenic tumor models." (PMID 31894857, 2020). "Despite increasing label indications across numerous cancer histologies, antibodies that block CTLA-4, PD-1, and PD-L1 are essentially ineffective in patients with advanced metastatic PDAC, linked mechanistically to a number of tumor-intrinsic and –extrinsic factors in the TME." (PMID 33304355, 2020). "The most common reasons of the low response rate are rare T cell infiltration in tumor or impaired antitumor T cells by other checkpoints, such as CTLA-4 or immune suppressive cells in tumor microenvironment or cancer cells insensitive to IFN-γ leading to no or low reactively expressed PD-L1 24-27." (PMID 31938049, 2020). "With respect to receptors/ligands, tumor-induced immune tolerance is mediated by changes in the expression of several inhibitory checkpoints including CTLA-4, PD-1, and its ligand (PD-L1), LAG-3, TIM-3 and its ligand (galectin-9), and adenosine A2a receptor (A2aR)." (PMID 32878115, 2020). "Indeed, these three checkpoint molecules are upregulated upon T-cell activation during the anti-tumor response, and tumor-infiltrating CTLA-4 + PD-1 + CD8 + T cells have been shown to contain the majority of tumor-antigen-specific T cells." (PMID 31974367, 2020). "We evaluated whether the immune checkpoint factors (PD-1 and CTLA-4) expression in the difference immune subpopulations changes with tumor growth progression." (PMID 32805718, 2020). "Indeed, the immune cell panorama within the tumor differentiates clinical response and resistance in both CTLA4 and PD-1 blockade." (PMID 31968651, 2020). "However, a previous study has unveiled that increased tumor immunogenicity modulates the response to CTLA-4 blockade." (PMID 32526888, 2020). "Interestingly, also CXCR4 inhibition results effective in reverting tolerogenic polarization of tumor microenvironment and in restoring sensitivity to CTLA-4 and PD-1 checkpoints inhibitors." (PMID 33123122, 2020).